FOXC1 (forkhead box C1)
Diseases named in the same sentence as FOXC1 in open-access papers (continued):
Sharing a sentence is not in itself a finding about the gene and the disease.
tumor (continued). "Additionally, the results also confirmed that the expression level of angiogenesis factor VEGF-A was reduced after FOXC1 and FOXCUT knockdown, which may indicate a possible role for FOXC1 and FOXCUT in tumor angiogenesis." (PMID 24889262, 2014). "Both methylated (n = 19) and unmethylated (n = 29) tumours showed significantly lower expression values compared to normal tissue (n = 28, both P < 0.001), indicating that the transcriptional inactivation of FOXC1 is an early event during tumour progression." (PMID 20056007, 2010). "Unlike the generally acknowledged tumor suppressor FOXA1, FOXC1 is considered to have dual roles in both oncogenesis and tumor suppression, with its specific behavior depending on its context within the pathway." (PMID 40003882, 2025). "In contrast, none of the genes found in tumor fragments to be regulated by translation (LOX, WISP), abundance (FOXC1, COL5A2, ITGA11) or buffering (SNAI2) were modulated by mTORC1 in U87-MG cells." (PMID 31052505, 2019). "There was a trend for the absence of methylation at ABCB1, FOXC1, PPP2R2B, and GSTP1 in both the basal-like and normal-like tumours, while IGF2, MLH1 and PTEN were hypomethylated in the basal-like tumours but not in the normal-like tumours." (PMID 20338046, 2010). "FOXC1 and GATA3 appear to be involved in a double-negative-feedback loop (mutual inhibition) that may influence the transition between luminal-like and basal-like tumor phenotypes." (PMID 27539783, 2016).
cancer (125 papers, 2005 to 2025). A tumor composed of atypical neoplastic, often pleomorphic cells that invade other tissues. "In summary, we have determined that FOXC1 functions as a cancer inhibitor in RCC and is linked to unfavorable prognosis." (PMID 39093497, 2024). "It has been recently identified that FOXC1, which is encoded by a gene located on chromosome 6p25, regulates several human cancers." (PMID 39596660, 2024). "Other members of the FOX family of TFs such as FOXA1, FOXM1, and FOXP1 are considered oncogenes and FOXC1 was implicated in cancer stemness through modulation of β-catenin signaling." (PMID 35349489, 2022). "Since that time, we and others have established the pivotal role that FOXC1 plays in coordinating the aggressive biology underlying cancer progression and metastasis in multiple cancers." (PMID 34540690, 2021). "FOXC1 is a pivotal transcription factor that has been functionally implicated to drive cancer metastasis and has been demonstrated to be an independent predictor of heightened metastatic risk, at the time of initial diagnosis." (PMID 34540690, 2021). "Recent studies have indicated that FOXC1, which is associated with a wide variety of cancers, is also strongly associated with mediating CSC activity." (PMID 34540690, 2021). "Using this strategy, we identified FOXC1 as the only statistically significant master regulator (BH-adjusted P < 0.05, a hypergeometric test) of the cancer hallmark “activating invasion and metastasis” dysregulated in TNBC." (PMID 33854062, 2021). "Clinical studies have also demonstrated that the elevated expression of FOXC1 was associated with poor prognosis in many kinds of cancers." (PMID 33802957, 2021). "After multiple initial reports that linked FOXC1 with EMT in various cancers, some recent reports have further refined our understanding that FOXC1 is in fact associated with a partial EMT phenotype comprising of hybrid E/M cells." (PMID 34540690, 2021). "Our analyses showed that a large proportion of TNBC-specific target genes are associated with multiple cancer hallmarks, and we were intrigued to uncover FOXC1 as the most significant regulator of activating invasion and metastasis." (PMID 33854062, 2021). "The transcription factor FOXC1 is a key regulator of several biological processes and its abnormal expression was found associated to poor survival in various malignant tumors and in the epithelial to mesenchymal transition (EMT) process." (PMID 32183847, 2020). "For brevity, we have focused on the most well-characterized miRNAs in this review; an extensive catalogue of miRNAs associated with FOXC1 in cancer but with currently unclear in vivo relevance was recently reviewed elsewhere." (PMID 30764547, 2019). "FOXC1 has been highlighted as an important transcriptional regulator involved in diverse tumorigenic processes, such as proliferation, invasion, and angiogenesis with high FOXC1 expression associated with poor prognosis in cancer patients." (PMID 31783879, 2019). "Crucially, gain of FOXC1 function is emerging as a recurrent feature of malignancy; FOXC1 overexpression is now documented in more than 16 cancer types, often in association with an unfavorable prognosis." (PMID 30764547, 2019). "Overexpression of FOXC1 has been reported in at least 16 types of cancer, often in association with a poor prognosis." (PMID 30764547, 2019). "FOXC1 is deregulated in different types of cancers and is often associated with poor prognosis in AML, cooperating with HOXA/B and consequently repressing the monocyte transcriptional regulator KLF4." (PMID 31234353, 2019). "More recently, however, studies have linked FOXC1 activity to the aggressive phenotype in cancer cells." (PMID 29487724, 2018). "In all the cancers discussed thus far, the ectopic overexpression of FOXC1 is always linked to increased aggression in cancer disease phenotypes, indicating FOXC1's potential as a major oncogene." (PMID 29487724, 2018).
cancer (continued). "Increased FOXC1 expression now appears to be linked to more aggressive cancer phenotypes in BLBC, HCC, HL, and NHL." (PMID 30564302, 2018). "FOXC1 has been implicated in numerous pathways that help determine the nature of different cancers, but the oncogenic mechanisms with which FOXC1 involved have yet to be completely elucidated." (PMID 29487724, 2018). "Three genes (P-cadherin, v-kit, FOXC1) were reported by the authors to be associated to a genes cluster over-expressed in the basal-like carcinomas and three genes (PTEN, Her2 and GRB7) to a genes cluster over-expressed in the Her2+ carcinomas." (PMID 21047405, 2010). "Comparison of transcriptomic changes between MOC2 control and EphB4 knockout cell lines showed higher expression of TGF beta receptors 1 and 2, NOTCH1, and FOXC1, a transcription factor implicated in cancer cell plasticity, treatment resistance, invasion, and epithelial-mesenchymal transition (EMT)." (PMID 39091728, 2024). "Additionally, the Forkhead box (FOX) family of transcription factors (FOXF1, FOXS1, FOXM1, FOXK1, FOXP4, and FOXC1) play a role in cell differentiation and proliferation and are implicated in cancer and drug resistance." (PMID 35854219, 2022). "FOXC1 has an important role in oncogenesis and is linked to poor prognosis in several cancer types." (PMID 35096062, 2022). "Beyond studies of association, FOXC1 has been demonstrated to play a causative role in cancer stem cell biology that contributes not only to an aggressive phenotype but to an aggressive clinical course as well, often culminating in metastatic dissemination and death." (PMID 34540690, 2021). "However, the molecular mechanism is not completely understood and future studies are warranted to clarify it and to assess the utility of FOXC1 as a potential cancer biomarker of induction chemotherapy outcome to improve risk-stratification of AML." (PMID 31234353, 2019). "FOXC1 was also found to be associated with drug resistance of cancers." (PMID 29552326, 2018). "Interestingly, while FOXC1 missense mutations that are associated with ARS usually reduce gene activity, increased FOXC1 function now appears to be often linked to more aggressive cancer phenotypes in BLBC, HCC, HL, and NHL." (PMID 29487724, 2018). "FOXCUT and FOXC1 could be represent the potential diagnostic markers and therapeutic targets in the cancer clinic." (PMID 24889262, 2014). "In TNBC, FOXC1 can co-regulate with L1 cell adhesion molecule (L1CAM) to promote cancer cell invasion, motility, and lung metastasis." (PMID 40822238, 2025). "The activities of SREBF1 and FOXA1 were higher in the primary cancer samples, while the activities of FOXC1 and TP73 were higher in normal samples, and the activities of transcription factors such as FOXA3 were higher in the CRPC samples." (PMID 39988626, 2025). "Prior research has indicated that FOXC1 acts as a hypoxia-activated TF, thereby facilitating cancer cell proliferation." (PMID 41030501, 2025). "A large number of clinical studies have shown that increased FOXC1 expression is closely related to poor prognosis in many cancer subtypes." (PMID 40176111, 2025). "FOXC1, a transcription factor aberrantly overexpressed in many cancers, drives growth, metastasis, and stem-cell-like properties in TNBC." (PMID 39171293, 2024). "In ccRCC, the upregulation of ENO2 is regulated by FOXC1, which promotes glycolysis and supports the Warburg effect—a metabolic shift observed in many cancers where cells rely on glycolysis for energy production even in the presence of oxygen." (PMID 39348357, 2024). "Abnormal expression of FOXC1 is involved in maintaining cancer stem cell proliferation, migration and angiogenesis." (PMID 38717954, 2024). "Increased activity of the transcription factor FOXC1 leads to elevated transcription of target genes, ultimately facilitating the progression of various cancer types." (PMID 39093497, 2024).
cancer (continued). "Targeting E3 ubiquitin enzymes for cancer therapy has long been considered an attractive mechanism-based drug discovery approach and the possibility of regulating FOXC1 activity via targeting ITCH remains to be seen." (PMID 39171293, 2024). "FOXC1, a well-known transcription factor, can increase the expression of tumor suppressor genes to demonstrate its anti-cancer properties." (PMID 39093497, 2024). "FOXC1 promotes cancer stem cell-like properties by upregulating β-catenin and activating WNT signaling." (PMID 39430239, 2024). "For instance, FOXC1 is associated with the epithelial–mesenchymal transition (EMT), which is critical for cancer metastasis." (PMID 39456780, 2024). "Numerous studies have confirmed that FOXC1 overexpression is frequently observed in cancers, with reports in more than 16 types of cancer, and is related to unfavorable prognosis." (PMID 39430239, 2024). "Here, we show that although FOXC1 regulates many cancer hallmarks in TNBC, its function is varied in different cell lines, highlighted by the differential response to CDK4/6 inhibitors upon FOXC1 loss." (PMID 39171293, 2024). "Research has demonstrated that FOXC1 is disrupted in various cancer, functioning as an oncogene in the advancement of the majority of cancer types." (PMID 39093497, 2024). "FOXC1 and L1CAM are known to be present in various types of cancer and have been implicated in cancer development based on in vitro experiments." (PMID 38183514, 2024). "This pattern was also observed in patients with TNBCs compared with those with HR-positive cancers (FOXC1: FC = 3.17; 95% CI, 2.86 to 3.50; P < .001; FOXA1: FC = −4.73; 95% CI, −5.30 to −4.16; P < .001) (eFigure 6A-D in Supplement 1)." (PMID 37796506, 2023). "Overexpression of FOXC1 has been found in several types of cancer, and elevated expression of FOXC1 is proposed to be a critical marker for TNBC/basal-like BC and a prognostic indicator for TNBC lung metastasis." (PMID 37208442, 2023). "The identified TFs, such as FOXC1, FOXL1, POU2F2, NFIC, NFkB1, MEF2A, GATA2, and E2F1, are mainly associated with different types of cancers and congenital disorders." (PMID 37026010, 2023). "In conclusion, our findings suggest anti‐inflammatory properties of FOXC1 in cancer cells and molecular mechanisms for FOXC1 as a novel regulator of IL‐1β and inflammation." (PMID 38107056, 2023). "In particular, the cancer-related lncRNA, such as SAMMSON and FOXCUT, belong to the gene network with the cancer-related transcription factor FOXC1." (PMID 37445678, 2023). "Currently, as a new cancer marker and therapeutic target, the regulatory role of FOXC1 in many types of cancer has been widely studied." (PMID 35733095, 2022). "This of course will need many years of focused effort to first identify the most promising therapeutic approaches to target FOXC1+ pro-metastatic cancers, followed by carefully conducted clinical trials to test and prove their effectiveness." (PMID 34540690, 2021). "Herein we discuss the current state of evidence that supports the argument that FOXC1 plays this role by virtue of being essential for the emergence, maintenance and proliferation of cancer stem cells (CSCs)." (PMID 34540690, 2021). "The focus of this review is to summarize and draw inferences from the body of literature that implicates FOXC1 as a transcriptional driver of cancer progression and metastasis." (PMID 34540690, 2021). "The other important factor whose role in cancer development and progression has begun to emerge is FOXC1." (PMID 34948036, 2021). "This transactivation of CCL2 by FOXC1 significantly promoted macrophage infiltration and cancer metastasis in HCC mouse models." (PMID 34540690, 2021). "We also highlight potential therapeutic strategies to target cancers that are, or have evolved to become, “transcriptionally addicted” to FOXC1." (PMID 34540690, 2021). "Some previous studies indicate that FOXC1 is a hypoxia-activated transcription factor to promote cancer cell growth." (PMID 33568052, 2021).
cancer (continued). "FOXC1 is an inducer of epithelial to mesenchymal transition in cancers, thereby contributes to tissue invasion, metastasis and relapse in cancer." (PMID 33450975, 2021). "FOXC1 expression in cancer tissues, has been demonstrated to be capable of identifying those patients who are at heightened risk of suffering metastatic recurrence." (PMID 34540690, 2021). "Over the course of the past decade, much has been learned regarding the important role played by the transcription factor FOXC1 in cancer." (PMID 34540690, 2021). "It is now well accepted that FOXC1 regulates a diverse set of biologically aggressive traits in cancer." (PMID 34540690, 2021). "Both of these FOXC1 biomarker status-driven interventions have the potential to exert a significant decrease in overall cancer related morbidity and mortality." (PMID 34540690, 2021). "It is reported that FOXC1 plays an important role in the occurrence, development, and migration of malignant tumors." (PMID 34957298, 2021). "FOXC1 induces cancer stem cell (CSC) properties in BLBC cells via activation of Smoothened-independent Hedgehog (Hh) signaling." (PMID 34540690, 2021). "Aberrant FOXC1 expression is involved in diverse tumorigenic processes, such as abnormal cell proliferation, cancer stem cell maintenance, cancer migration, and angiogenesis." (PMID 34540690, 2021). "In summary, these findings demonstrate that a collection of SE-associated TNBC genes (EGFR, FOSL1, FOXC1 and MYC) play a significant regulatory role in the proliferation, survival, invasion and metastasis of these CDK7-sensitive and TNBC-enriched cancers." (PMID 34540690, 2021). "Cell crosstalk mechanisms pertinent to FOXC1+ cancers are discussed in more detail in a separate section below." (PMID 34540690, 2021). "From an ever-expanding understanding of the functional and mechanistic role of FOXC1 in cancer, we have also developed an appreciation of its potential application as a powerful prognostic biomarker." (PMID 34540690, 2021). "From the first report of its central role in aggressive BLBCs more than 10 years ago, we have come to understand that FOXC1 plays a pivotal functional role in more than 16 different cancer types." (PMID 34540690, 2021). "A positive correlation between FOXC1 expression and lysyl oxidase (LOX) expression was established in NSCLC patient samples wherein FOXC1 activated LOX transcription to drive cancer progression through the FOXC1-LOX axis." (PMID 34540690, 2021). "We present evidence of how FOXC1 plays a functionally important role in mediating a wide variety of cancer traits all of which are, essentially, cancer stem cell traits." (PMID 34540690, 2021). "Consistent with our results, there is evidence that FOXC1 overexpression contributes to an increased capacity for cancer cell survival and proliferation." (PMID 34082653, 2021). "Conversely, siRNA-mediated knockdown of FOXC1 practically abolished metastatic propensity in most of these models, confirming the critical dependence of these cancers on FOXC1 to drive the metastatic program." (PMID 34540690, 2021). "Further evidence to support such an approach was obtained in another preclinical study wherein the Wnt signaling pathway (a CSC-associated pathway) was therapeutically inhibited in an in vitro FOXC1+ cancer model." (PMID 34540690, 2021). "Despite the importance of FOXC1 in human AML, and more broadly in solid malignancies, the mechanisms by which FOXC1 confers adverse outcomes in human cancers remain largely unexplored." (PMID 34551306, 2021). "FOXC1 is up-regulated in retinoic acid-induced differentiation of F9 Embryonal Carcinoma (EC) cells; furthermore, FOXC1 specifically inhibits the core pluripotency factor Nanog by binding to the proximal promoter." (PMID 33668324, 2021). "FOXC1 is also an important biomarker of cancer which plays a central role in cell proliferation, cell differentiation, cell migration, survival and death and metastasis." (PMID 33193605, 2020).